CD4 (CD4 molecule)
Diseases named in the same sentence as CD4 in open-access papers (continued):
Sharing a sentence is not in itself a finding about the gene and the disease.
tumor (continued). "The role of LAG-3 expression on circulating NK cells, as well as the expression of LAG-3 ligands on tumor cells and the early modulation of circulating cytotoxic CD4+ T cells warrant further investigation as exploitable predictive biomarkers for dual PD-1 and LAG-3 blockade." (PMID 38336861, 2024). "Furthermore, mature MDSCs effectively promote CD4+ Th1 differentiation to sustain CTT-triggered persistent anti-tumor immunity." (PMID 38791188, 2024). "suggests that smoking may activate mast cells and CD4 memory T cells, leading to tumor growth and progression." (PMID 38601154, 2024). "Interestingly, MβCD alone increased both the ratio and activity of tumor-infiltrating CD8+ T cells while increasing the activity of CD4+ T cells." (PMID 39343834, 2024). "To examine whether vaccine-induced tumor protection was dependent on CD4+ or CD8+ T cells in the effector phase, we performed in vivo depletion of these two T cell subsets in uniHELP- and neoHELP-immunized mice around the time of MC-38 inoculation." (PMID 39040850, 2024). "Anti-tumor immunity is represented by varied subsets of TILs such as CD4+ and CD8+ T cells." (PMID 38779258, 2024). "However, Ki67- tumour cells were in closer contact with CD4 + T cells (Ki67 + tumour cell/ CD4 + T cell correlation coefficient = -0.0339, Ki67- tumour cell/ CD4 + T cell correlation coefficient = 0.1932)." (PMID 38311785, 2024). "In addition, IL-10 induces the overexpression of Foxp3 in CD4+ T cells, increasing the number of Tregs in the tumor." (PMID 39085255, 2024). "DCs activate CD8+ T cells by recognizing and presenting antigens specific to tumor cells, promoting the differentiation of CD4+ T cells into a variety of Th cells, and secreting cytokines such as IL-12.56, 57, 58 Moreover, DCs can mediate the generation of Tregs." (PMID 39263534, 2024). "Moreover, the CD4 CTL gene signature was correlated with anti-PD-L1 therapy response in patients, supportive of the CD4 CTL function in anti-tumor immune response." (PMID 38968186, 2024). "However, recent studies have found that some cancer cells also express HLA-II in an IFN-γ-inducible manner, and the presentation of HLA-II neoantigens by cancer cells to CD4+ T cells plays an important role in activating tumor immunity." (PMID 39682229, 2024). "The DEFA1B gene belongs to the α-defensin subgroup, which is known to promote tumor cell proliferation, contributing to tumor progression and invasiveness, as well as influencing tumor microenvironment due to their chemotactic properties (CD4+, CD8+, immature DC, monocytes)." (PMID 38398111, 2024). "The shCTDSPL2 group exhibited increased infiltration of CD4+ T cells into tumor tissues." (PMID 39209829, 2024). "In tumor microenvironment, CD4+ CD25low T cells and CD4+ CD25- T cells may get induced for FOXP3 expression and converted to CD4+ CD25+ Tregs." (PMID 38571964, 2024). "Similarly, CD4+ T cells can actively respond to mutant antigens, so mediating the tumor elimination." (PMID 38685033, 2024). "For safety concerns, it is worth noting that instead of using live parasites, Pyan and colleagues demonstrated that treatment with soluble T. gondii or T. gondii profilin in pancreatic cancer tumors in C57BL/6J mice decreased tumor volume and increased tumor infiltration with CD4+ and CD8+ T cells." (PMID 39367471, 2024). "Depletion of NK cells showed minimal antitumor effects, whereas the depletion of CD4+ or CD8+ T cells resulted in a significant decrease in both tumor growth inhibition and survival benefit, suggesting that T cells play a critical role in cGAS-initiated immunotherapy." (PMID 38518087, 2024). "Comparatively, the high-risk group demonstrates elevated proportions of CD8+ T cells, activated CD4+ memory T cells, and Tregs, which serve as effector T cells, fostering tumor immune activation and cytotoxicity against tumor cells, thereby favoring positive clinical outcomes for patients." (PMID 38464749, 2024).
tumor (continued). "Furthermore, flow cytometry analysis revealed that RocA significantly increased the tumor-infiltrating lymphocytes (TILs), including both CD4+ and CD8+ T cells." (PMID 38833034, 2024). "In this study, tumor immunological profiling following bacterial depletion revealed an increase in anti-tumor immune lymphocytic cells (CD3+CD4+IFNγ+, CD3+CD8+IFNγ+, and CD3+IFNγ+), while a decrease in pro-tumorigenic IL17a (IL17a + CD3 +) and IL10(IL10 + CD4 + CD3 +)." (PMID 39044834, 2024). "Notably, CD4+ T cells effectively impede tumor cell division by arresting their cell cycle at the G1/S phase, inhibiting tumor growth." (PMID 38292868, 2024). "Notably, these same Vβ receptor subtypes were enriched in both CD4+ and CD8+ T cells, suggesting a polyclonal T cell response to tumor-associated antigens in Mgat5-WT tumors." (PMID 38912584, 2024). "Additionally, these mice display a significant delay of T-ALL progression with respect to the N3tg controls, as evidenced by the reduction in tumor CD4+CD8+ DP T-cell number, due to a cell autonomous enhancement of their apoptotic rate." (PMID 39337370, 2024). "Further, significantly more CD4-positive or CD8-positive CD3+CD45.1− cells expressed PD-1 in the combination treatment group when compared to the CART-alone group in the PDA7940b or B16-huCD19 tumor models, respectively." (PMID 38730243, 2024). "The following translocation of Enterococcus hirae and Lactobacillus Johansonii to tumor-draining lymph nodes (TDLNs) induced differentiation of CD4+T-cells to Th17 in the tumor microenvironment (TME), thus enhancing the anti-fibrosarcoma efficacy of CTX in vivo." (PMID 38794174, 2024). "CD4 T cells, due to their numerous subtypes, have diverse roles; on one hand, they can help tumors escape and suppress anti-tumor immune responses, while on the other hand, they can promote anti-tumor immune responses and inhibit tumor growth." (PMID 39493752, 2024). "Contrary to previous findings, an interesting study revealed that IKKβ deficiency in CAFs promotes intestinal epithelial cell proliferation, inhibits tumor cell apoptosis, increases CD4+Foxp3+ regulatory T cell accumulation, and stimulates angiogenesis, thereby facilitating colonic tumor growth." (PMID 39493763, 2024). "Additionally, we found that CD8+ and CD4+ T cells located within the tumor compartment are cordoned off in stromal bands, and thus sequestered from carcinoma cells." (PMID 38429349, 2024). "Our results demonstrated that T cells are spatially excluded from the carcinoma compartment, with the highest density of CD8+ cytotoxic and CD4+ helper T cells found in adjacent non-tumor liver (NTL) and, intra-tumoraly, within dense fibrous stromal bands sequestered from tumor cells." (PMID 38429349, 2024). "After only three doses BIW, we could still recover a smaller tumor and, in tumor sections, showed an increase in penetration of CD4+ and CD8+ T-cells deeper into the remaining tumor that was not evident in animals treated with non-silencing siRNA." (PMID 38204925, 2024). "The anti-tumor effect triggered by vaccination was largely dependent on CD4+ T cells." (PMID 38793784, 2024). "IRE induced the release of damage-associated molecular patterns (DAMPs) and lead to a 2.3-fold increase of interferon (IFN)γ-secreting tumor antigen-specific splenocytes in long-term surviving mice compared to treatment-naive, as well as a greatly increased frequency of CD4 and CD8 memory cells." (PMID 39610376, 2024).
tumor (continued). "To determine the abundance of immune cells in the tumor, we used the function cytomappershiny from the package cytomapper of R. We selected neutrophils, CD4+ and CD8+ T-lymphocytes and myeloid cells (except neutrophils) manually based on the expression of specific markers." (PMID 38430241, 2024). "B lymphocytes (CD19+ B cells) regulate humoral immunity, influence CD4+ T cell function, and may impact tumor progression, although their specific effect on ovarian cancer remains incompletely understood." (PMID 39000195, 2024). "Conversely, TNF-α fosters dendritic cell maturation and subsequent T cell activation, while IL-12 is associated with improved CAR-T cell functionality, increased infiltration of CD4+ T cells, and reduced T-regulatory cell frequency within the tumor microenvironment." (PMID 38994360, 2024). "CD4+ regulatory T cells (Tregs) are immunosuppressive cells in the tumor microenvironment." (PMID 38892423, 2024). "However, DCs are often heterogeneous and have multifaceted functions in immunomodulation by priming and regulating the activation, differentiation, and function of tumor antigen-specific CTLs, CD4+ T helper cells, regulatory T cells, and B cells." (PMID 39617785, 2024). "In addition, the CD4:CD8 T-cell ratio was significantly lower in the tumor due to increased number of CD8+ T-cells." (PMID 38173045, 2024). "The absence of Cdk5 induces the expression of PD-L1 transcriptional inhibitors (IRF2 and IRF2BP2), maintaining transcriptional repression of PD-L1 after IFN-γ stimulation, resulting in increased infiltration of CD4 T cells and promoting anti-tumor immune responses." (PMID 38762484, 2024). "- OV-mOX40L inhibited tumor growth in vivo- Local treatment of OV-mOX40L stimulated intratumoral immune cells.- OV-mOX40L activated CD4+ T cells and CD8+ cytotoxic T cells and reduced Treg proportion leading to switching the TME to a more pro-inflammatory state." (PMID 38464532, 2024). "While it is important to understand exhaustion in cytotoxic effector cells, as they are responsible for a large part of the direct cytotoxicity within a tumor, it is becoming increasingly apparent that exhaustion of CD4+ T cells likewise plays a critical role in anti-tumor immunity." (PMID 39689157, 2024). "Similarly, we have also demonstrated that HS treatment upregulated Th1 and Th17 effector CD4+T cell immune responses leading to tumor immune elimination and decreasing tumor progression." (PMID 38891044, 2024). "IFN-I-producing CD4+ T cells are present in diverse T-cell-infiltrated cancers and likely deliver “help” signals to CTLs locally, according to their transcriptomic profile and colocalization with “helped/licensed” cDCs and tumor-reactive CD8+ T cells." (PMID 38383773, 2024). "It has been demonstrated that there is a gradient decrease in T cell infiltration from the periphery to the center of the tumor, and that the total number of intraepithelial infiltrating CD4+ T lymphocytes serve as an independent staging and prognostic indicator for CCA." (PMID 39845973, 2024). "In immune cell infiltration analysis, we found that a variety of immune cells, including CD8+T cells, plasma cells, activated NK cells, and macrophages M2 were more abundant in normal tissues, while macrophages M1, T cells CD4+ memory resting, and γδ T cells were more infiltrated in tumor tissues." (PMID 38370403, 2024). "Among CD4+ T cells, we noted no changes to the number of tumor-infiltrating FOXP3+ Tregs, and CD4+ FOXP3- effectors in the tumor parenchyma following the combination treatment, suggesting that only CD8+ T cells are critically implicated in the observed phenotype." (PMID 38509063, 2024). "Type 1 cDCs (cDC1) are the major subset that can cross-present antigens and activate CD8 T cells through the major histocompatibility complex class I (MHC-I) pathway, and activate CD4 T cells through the MHC-II and CD4 signaling pathway to induce adaptive anti-tumor immune responses." (PMID 39262952, 2024).
tumor (continued). "Further, splenic CD4 signal (SUVmean on day 6) was negatively correlated with terminal tumor mass (r = 0.33, p = 0.04) in the 4T1 model, indicating that higher spleen CD4 + cell presence was related to smaller tumor sizes." (PMID 38918836, 2024). "In contrast, CD4_CTL cells were more prevalent in normal tissues than in tumor tissues." (PMID 38948071, 2024). "Moreover, our findings indicate that the prognostic significance of MCU is modulated by the presence of Th1, Th2, mesenchymal stem cells (MSC), macrophages, CD4 + T-cells, CD8 + T-cells, B-cells, and tumor mutational burden (TMB)." (PMID 38632642, 2024). "In addition, effector CD4 T cells in RelRef AML were associated with better outcomes and responses, and tumor-infiltrating CD4 T cells were found to exhibit T helper and cytotoxic activity." (PMID 38391202, 2024). "This begins with the presentation of tumor antigens by the antigen‐presenting cells (such as DCs in the case of DC‐based vaccines) to naive T cells in the lymph nodes that enables the activation of both helper CD4+ T cells and cytotoxic CD8+ T cells." (PMID 39215399, 2024). "Besides, we applied depleting antibodies against CD8+ and CD4+ T cells to discern the specific contributions of immune modulation to tumor outgrowth." (PMID 38816360, 2024). "Interestingly, CD4+ T cells can drive strong anti-tumor immunity upon ICB in preclinical models of MMRd tumors with defective or low expression of MHC-I, which cannot be recognized by CD8+ T cells." (PMID 39544936, 2024). "As these cells express MHC class II molecules, it is most likely that both resident macrophages and microglial cells participate to the tumor antigen presenting function necessary to stimulate tumor specific CD4 + T cells, thus triggering the adaptive immune response leading to GBM rejection." (PMID 39334370, 2024). "Furthermore, immunohistochemistry showed that the expression of CD4/CD8 was significantly increased in the tumor tissues of CPSF6 depleted Hep3B cells inoculated in BALB/c mice compared to that in the untreated control." (PMID 38993554, 2024). "Functional studies will also allow us to assess whether C002 improves the response of tumor antigen-specific CD4(+) T cells." (PMID 38895115, 2024). "Additionally, increased miR-155 levels in various immune cell populations, including CD4+ and CD8+ T cell, M1 tumor-associated macrophages (TAMs), dendritic cells (DCs), and natural killer cells, can enhance their anti-tumor activity." (PMID 38972995, 2024). "Furthermore, ALDH2 expression in tumor cells is significantly and positively correlated with the infiltration of immune cells, including CD4+ T cells, CD8+ T cells, neutrophils, B cells, and macrophages in various tumor types." (PMID 39735553, 2024). "This implies that older patients may have a decreased presence of CD4+ T cells and macrophages in the tumor center, along with lower PD-L1 expression, which could impact the efficacy of immune responses and immunotherapy." (PMID 39338178, 2024). "On the other hand, the increase in the number of CD4+ T cells may reflect the greater activation of T lymphocytes in response to tumor invasion in the lymph node." (PMID 38913547, 2024). "In addition, miR-214 levels in CD4 (+) tumor T cells from CTCL patients were found to be substantially higher than those in healthy individuals." (PMID 39256366, 2024). "LAG-3 and MHC class II binding contributes to the recruitment of tumor-specific CD4+ T cells." (PMID 39796650, 2024). "Even if the levels of IFNγ are not very high in the sera of Hc-treated mice, the local intra-tumor IFNγ production by tumor-infiltrated CD4 Th1, CD8 cytotoxic T lymphocytes, and NK cells induced the generation of specific antitumor CTLs, responsible for tumor growth suppression." (PMID 38786612, 2024). "Interestingly, tumor-infiltrating Th1 cells (IFN-γ+ TNF-α+ CD4+ T cells) were found to be increased in the DT-mediated Foxp3+ Treg-ablated group in comparison to the control." (PMID 39247196, 2024).
tumor (continued). "However, similar to Foxp3+CD4+ T cells data, the presence of IL17A+CD4+ T cells in the tumour microenvironment is associated with potential anti-tumour, as well as pro-tumourigenic effects due to their plasticity." (PMID 39409156, 2024). "Tumor-educated DCs can inhibit CD4(+) T cell proliferation and suppress T cell response, β-glucan can downregulate tumor-educated dendritic cells surface PD-L1 expression in LLC mice, which enhances priming of Th1 cells and CD8+ T cells while decreasing Treg cell differentiation." (PMID 38426097, 2024). "increased the effectiveness of a tumor vaccination by integrating CD4+ T cells, which may suggest that appropriate vaccines or drugs can be designed to increase the proportion of activated CD4 memory T cells to effectively exert antitumor effects." (PMID 38493212, 2024). "M1/M2 macrophages, N1/N2 neutrophils, CD4+ T cells (T-helper), CD8+ T cells (T-cytotoxic), FOXP3+CD4+ Tregs, and antigen-presenting DCs are widely known infiltrating immune cells and are implicated in a spectrum of tumor pathologies." (PMID 38730579, 2024). "MDSCs control the inhibition of tumor activity in CD4+ and CD8+ T lymphocytes." (PMID 38835055, 2024). "Previous research has shown that MDM2 protein, whether expressed in tumor cells or CD4 + T cells, negatively regulates tumor-infiltrating CD4 + T cells and contributes to immune evasion." (PMID 38281981, 2024). "Additionally, immunohistochemical staining of tumor tissues confirmed that the combination treatment of aAGd-NWs+RT substantially improved the infiltration of both CD4+ and CD8+ T cells." (PMID 38724527, 2024). "Among them, CD4 T cells serve as the core of the body to initiate immune protection, which can inhibit tumor progression by enhancing the tumor-killing activity of anti-tumor effector cells." (PMID 38243040, 2024). "Given the significant changes in T cell abundance by Prmt3-KO and PRMT3 inhibition, we then examined whether the effects of Prmt3-KO and PRMT3 inhibition on tumor progression were mediated by CD8+ or CD4+ T cells." (PMID 39256398, 2024). "Nrn1 mRNA level was significantly increased among tumor-associated Treg cells and non-Treg CD4 cells compared to cells from peripheral blood." (PMID 39565188, 2024). "CD1c+ cDC2s may also be restricted by regulatory T cells (Tregs) in their ability to recruit CD4+ T-cells to the tumor." (PMID 38261139, 2024). "Consequently, the lymph node sends CD8+ (cytotoxic) and CD4+ (helper) T cells to the tumor microenvironment." (PMID 39627216, 2024). "Notably, CXCL signaling network exhibit heightened activity in mediating communication between CXCL10+ M1 macrophages and CD4+T cell, with significantly elevated activity within the tumor group compared to the normal group." (PMID 39170612, 2024). "We measured the densities of CD8+ and CD4+ T cell populations within each tumor." (PMID 38523774, 2024). "In addition, we demonstrated a correlation between the activities of Hypo-MS4 in cancer cells and the fractions of regulatory CD4 + T cells with the expression levels of immunological genes in the tumor immune microenvironment." (PMID 38566132, 2024). "The second layer returns tumor, immune (naïve B, memory B, CD4 naïve T, CD4 memory T, regulatory T, CD8 naïve T, CD8 memory T, monocyte, dendritic cell, natural killer, basophil, eosinophil, and neutrophil cells), and angiogenic (endothelial, epithelial, and stromal cells) cell-type proportions." (PMID 38173042, 2024). "Conversely, CD4+ T cells and B cells were located far from the tumor mass." (PMID 38338669, 2024). "Additionally, the presence of antigen-specific CD4+ Tregs within tumors can greatly inhibit immune responses, ultimately resulting in immune tolerance toward tumor cells." (PMID 39664195, 2024).